INS (insulin)
Diseases named in the same sentence as INS in open-access papers (continued):
Sharing a sentence is not in itself a finding about the gene and the disease.
metabolic syndrome (continued). "Elucidation of these pathways will help synthesize analogues that could specifically enhance the buffering or aldehyde quenching capacity in the skeletal muscle and affect the insulin responses during metabolic syndrome." (PMID 32977552, 2020). "Similarly, another study reported a significant increase in insulin sensitivity, together with altered microbiota composition, in patients with metabolic syndrome who received allogenic FMT from lean donors compared to those who underwent autologous FMT." (PMID 32517023, 2020). "They tightly control insulin release, glucagon secretion, hepatic gluconeogenesis, and glycogenolysis, and elevated levels of these catecholamines are related to metabolic dysregulation and metabolic syndrome." (PMID 33335492, 2020). "In addition, post-hoc analyses among those with metabolic syndrome at baseline showed transient improvements in glucose metabolism and insulin sensitivity at 6 weeks, and resolution of metabolic syndrome in most FMT-treated participants by 26 weeks." (PMID 33346848, 2020). "Moreover, administration of 500 g of trans-resveratrol three times a day for 90 days in 24 metabolic syndrome subjects resulted in decreased weight, fat mass, BMI index, waist circumference, area under the curve of insulin and total insulin secretion." (PMID 32230718, 2020). "One of the consequences of the chronic exposure to glucose solutions are disturbances in the metabolism of carbohydrate as insulin resistance, dyslipidemia, higher needs of insulin in diabetic patients and even an elevation in fasting glucose and HbA1C in non-diabetic patients." (PMID 30890947, 2019). "In addition, this animal model of metabolic syndrome is characterized by increased leptin and triglycerides levels, but lower adiponectin and normal insulin levels." (PMID 31131281, 2019). "Insulin resistance is a condition wherein cells do not respond appropriately to insulin, further characterized by a risk of developing metabolic syndrome such as cardiovascular disease and type 2 diabetes." (PMID 30679431, 2019). "In this study, we hypothesised that adipose tissue from horses with metabolic syndrome would be dysfunctional with adipocyte hypertrophy, fibrosis, inflammation and altered insulin signalling." (PMID 30866087, 2019). "Furthermore, BMI, history of hypertension and dyslipidemia, change in HbA1c, and treatment with basal insulin analogs were independent predictors of change in PBR." (PMID 31284526, 2019). "The connecting link between PCOS and metabolic syndrome is resistance to insulin." (PMID 34466481, 2019). "The Dex-treated rats’ heart proteomes showed an increase in the levels of the enzyme hydroxysteroid 11-beta dehydrogenase 1(HSD11B1), which is known to augment GC action and increase the adverse effects of the drug, leading to increased insulin resistance, dyslipidemia, and hypertension." (PMID 31247941, 2019). "Indeed, elevations of insulin concentration were shown to prospectively precede the development of these metabolic disorders and the role of IR in metabolic syndrome was shown to be related to low insulin sensitivity." (PMID 31331009, 2019). "The amelioration of dyslipidemia and lowering of oxidative stress, inflammatory processes, insulin sensitivity, and remnant lipoproteins levels may lead to the reduction in cardiovascular burden." (PMID 31752189, 2019). "Indeed, in certain types of obese diabetic rodents, O3 exacerbates their already compromised insulin sensitivity and also induces adipose tissue and systemic inflammation, other characteristics of the metabolic syndrome." (PMID 31867021, 2019). "We tested the hypothesis that the anti-malarial drug chloroquine, which activates the kinase ATM, improves insulin sensitivity and decreases atherosclerosis in humans with metabolic syndrome." (PMID 31384309, 2019).
metabolic syndrome (continued). "Adipose tissue is an endocrine organ which can produce several adipokines that can modulate insulin sensitivity and contribute to the pathogenesis of MetS, DM, dyslipidemia, inflammation, endothelial dysfunction, coronary artery disease (CAD), and atherosclerotic stroke." (PMID 31803136, 2019). "However, a significant gap of knowledge exists between the underlying cellular and molecular mechanisms leading to postprandial dyslipidemia and insulin resistance in aged organisms." (PMID 31405194, 2019). "Postprandial lipemia, which is mainly related to the increase in chylomicron production, is frequently elevated in individuals at high cardiovascular risk such as obese or overweight patients, type 2 diabetic patients and subjects with a metabolic syndrome who share an insulin resistant state." (PMID 31181761, 2019). "The PNPLA3 rs738409 variant does not modify the disease through changes in insulin sensitivity, metabolic syndrome, body mass index, or dyslipidemia." (PMID 31877771, 2019). "The possible mechanisms might include vascular endothelial injury, insulin resistance, sympathetic activation, neurohumoral changes, inflammation, oxidative stress, dyslipidemia through chronic intermittent hypoxia." (PMID 30819182, 2019). "In another study, a healthy diet containing one daily serving of nuts for 12 weeks had little effect on lipid profile of metabolic syndrome (MetS) patients but led to improvement on insulin sensitivity and a marginal anti-inflammatory effect, in combination with moderate weight loss." (PMID 31505825, 2019). "Men engaging in 3 h/week of moderate or vigorous LTPA were half as likely as sedentary men to have the metabolic syndrome after adjustment for major confounders (age, BMI, smoking, alcohol, and socioeconomic status) or potentially mediating factors (insulin, glucose, lipids, and blood pressure)." (PMID 31331009, 2019). "Cardiovascular-risk factors are constant in hepatitis C related to liver disease, and we could observe that, in our cohort of patients, 13.1% are diabetics (of whom 5.4% are insulin-dependent) and 48 met metabolic-syndrome criteria at two years." (PMID 31426495, 2019). "Gut microbiota transplantations from lean donors to recipients with metabolic syndrome have shown to increase Roseburia and butyrate levels together with improved insulin sensitivity, thus suggesting the importance of butyrate-producing bacteria for blood glucose regulation in humans." (PMID 31199857, 2019). "Indeed, hepatic CB1 receptor is involved in development of diet-induced steatosis, dyslipidemia, and insulin and leptin resistance." (PMID 31121839, 2019). "In the current study, we corroborated L-arabinose’s efficacy in HFD-induced MS, specifically in reducing body weight gain and fat weight, improving insulin sensitivity, alleviating liver steatosis and dyslipidemia and decreasing serum inflammatory cytokines in mice on HFD." (PMID 31847305, 2019). "The amelioration of dyslipidemia and the lowering of oxidative stress, inflammatory processes, insulin sensitivity and remnant lipoproteins levels may lead to the reduction in cardiovascular burden." (PMID 31752189, 2019). "At study entry and before starting pasireotide, the patient was affected by overweight, hypertension, treated with nebivolol (5 mg/die) and canrenone (100 mg/die), DM, treated with short-acting (32 IU/die) and long-acting insulin (15 IU/die), and mixed dyslipidemia, treated with diet." (PMID 30968338, 2019). "Fasting serum insulin levels, as an early hallmark of the metabolic syndrome, were not significantly altered when mice fed early transient HFD or R-HFD reached adulthood." (PMID 31003943, 2019). "The comparison of the laboratory’s parameters and echocardiographic parameters revealed that fasting plasma glucose, HDL, Triglyceride, GGT, AST, ALT and fasting insulin levels were significantly greater in the metabolic syndrome group (for all comparisons, p < 0.01)." (PMID 30862094, 2019).
metabolic syndrome (continued). "Indeed, several studies have reported that circulating IGFBP-2 was related to insulin sensitivity, metabolic syndrome and antidiabetic effect by regulate the expression of leptin gene." (PMID 31547433, 2019). "Increased 11βHSD activity could lead to development of metabolic syndrome.11 β HSD knock off transgenic mice have higher insulin sensitivity." (PMID 30678666, 2019). "Excessive fat intake induces ectopic lipid accumulation in skeletal muscle, and may consequently result in low insulin sensitivity, eventually IR and related metabolic syndromes." (PMID 31417429, 2019). "Finally, eleven CpG sites were associated with metabolic syndrome: cg08862778 (MTOR), cg11322849 (INS), cg07199894 (ULK1), cg11658986-cg04149773 (ADCY6), cg14862787-11301281 (CREB5), cg14844401-cg20300093 (ADCY5), cg01284192 (IGF1R) and cg08128650 (RELA)." (PMID 30926763, 2019). "The aim of the study from 2002 was to investigate whether t10c12 CLA or a mixture of CLAs could improve insulin sensitivity, lipid metabolism or body composition in obese patients with metabolic syndrome symptoms." (PMID 31574903, 2019). "Cognition-related disorders, such as AD, are known to be affected by lowered insulin sensitivity and increased inflammatory load in the brain; presence of diseases such as obesity and metabolic syndrome gives rise to systemic inflammation which eventually passes through the BBB." (PMID 30909971, 2019). "In T1DM, a BMI ≥27.5 kg/m2 was associated with increased rates of hypertension, dyslipidemia, microalbuminuria, and increased insulin demand, whereas glycemic control was not affected." (PMID 30617710, 2019). "The aim of this study was to compare acute effects of turnip rapeseed oil rich with mono- and polyunsaturated fatty acids and cream on postprandial triglyceride levels and post-glucose load measures of insulin sensitivity in population of men with metabolic syndrome." (PMID 29755591, 2018). "We aimed to determine the association between fasting insulin (FI) levels and metabolic syndrome (MetS) in non-diabetic middle-aged and elderly adults in a community in Taiwan." (PMID 29724734, 2018). "Set-aside the diagnostic criteria established by the NCEP-ATPIII in 2003 —waist circumference, plasma glucose, plasma triglycerides, high-density-lipoprotein (HDL) cholesterol, and blood pressure—a core component of the metabolic syndrome is impaired insulin sensitivity." (PMID 30213062, 2018). "In regards to the glucose and insulin, as a component of the ‘Metabolic-Syndrome’ profile, some data suggest that elevated serum levels of these markers may be considered as predictors for breast cancer, however, there is not enough evidence." (PMID 30572623, 2018). "Recent studies have shown pleiotropic associations of LIPC single nucleotide polymorphisms (SNPs), which included lipid profiles, hepatic lipase activity, serum insulin levels, insulin sensitivity, markers for oxidative stress, metabolic syndrome and atherosclerotic cardiovascular diseases." (PMID 30410583, 2018). "Other studies have explained that the association between metabolic syndrome and EAT thickness may be attributed to the endocrine action of the EAT, which also affects insulin sensitivity, designating EAT as a biologically active organ." (PMID 29325562, 2018). "In summary, our data suggest that insulin contributes to the dysregulation of the HPA axis observed in metabolic syndrome by directly increasing the production of adrenal gland hormones through upregulation of SF-1 and the steroidogenic genes important for steroid hormone synthesis." (PMID 29567944, 2018). "In addition, it is stated that the reduction of testosterone levels improves endothelial dysfunction, body weight, and dyslipidemia and insulin sensitivity in these patients." (PMID 30217229, 2018).
metabolic syndrome (continued). "They contribute to the occurrence of a cluster of disorders known as the metabolic syndrome—abdominal obesity, hypertension, dyslipidemia, and disturbed metabolism of glucose or insulin—which in turn accounts for a significant share of the global burden of disease." (PMID 30115131, 2018). "In addition, a whole grain cereal-based diet significantly lowered postprandial plasma insulin concentrations in individuals with metabolic syndrome." (PMID 30275350, 2018). "LPA was found to have a favorable (++) association with waist circumference (WC) [eight of 12 studies (67%)], triglycerides [eight of 11 studies (73%)], insulin [five of six studies (83%)], and presence of metabolic syndrome [five of seven studies (67%)], whereas an inconsistent (?)?" (PMID 29986718, 2018). "Moreover, Santos and colleagues reported that Mas-knockout mice presented with dyslipidemia, as well as increased levels of insulin and leptin, and that Mas deletion led to glucose intolerance and reduced insulin sensitivity." (PMID 29618822, 2018). "Here, we show that Aloxe3 is activated by the adaptive hepatic fasting response and is itself sufficient to enhance insulin sensitivity, increase basal caloric expenditure, and reduce diet-induced weight gain and fat accumulation, hepatic steatosis, and dyslipidemia." (PMID 30135298, 2018). "Resistance training may also improve hypertension, dyslipidemia, insulin and glucose regulation, which are important comorbidities of T2D associated with cognitive impairment." (PMID 29387262, 2018). "Considering that glucose intolerance and reduction in insulin sensitivity commonly occur together with basal dysglycemia and dyslipidemia, we assessed these two aspects in rats treated with bezafibrate to verify the impact of such treatment on these parameters." (PMID 30532777, 2018). "Thus, in this study, our aim was to evaluate the possible metabolic activity of the compound in a dyslipidemia and dysglycemia model, related to insulin signaling in liver and adipose tissue, as well as its toxicological and pharmacological effects." (PMID 30026756, 2018). "The study of the metabolic syndrome is particularly challenging during the transition period to adulthood given the rapid change in body composition and the gender-related developmental changes in insulin resistance." (PMID 29853885, 2018). "Elevated levels of Serpinf1 may serve as a regulator of metabolic syndrome and prolonged administration leads to adipose tissue lipolysis and reduced insulin sensitivity." (PMID 28575190, 2018). "This population of stem cells, because of their multipotent character, anabolic activity and immunomodulatory effect as well as the ability to differentiate into insulin-producing cells, is a promising candidate in the field of endocrine disorders, including type 2 diabetes and metabolic syndrome." (PMID 29611042, 2018). "Primary NAFLD was a strong risk factor for impaired glycemic control at the population level independently of a wide range of confounders including insulin, adipocytokines, metabolic syndrome, physical activity, weight change during follow-up, and dietary intake." (PMID 29151224, 2018). "Moreover, hepatic Aloxe3 expression mitigated diet-induced dyslipidemia, and db/db mice expressing Aloxe3 exhibited attenuated weight gain, enhanced basal caloric expenditure, and PPARγ-dependent insulin sensitivity." (PMID 30135298, 2018). "Increased capacity for adipose tissue thermogenesis is generally accepted to be protective against insulin resistance and dyslipidemia but to which extent the regulation of browning by TZDs mediates insulin sensitization remains unclear." (PMID 29973382, 2018). "In addition to having immune (down)regulating functions, testosterone therapy reduces inflammatory cytokine production and improves insulin sensitivity in obese and metabolic syndrome males." (PMID 29566712, 2018).
metabolic syndrome (continued). "Moreover, this diet can provide protective effects on metabolic syndrome and its components and improves insulin sensitivity and hepatic steatosis in patients with NAFLD." (PMID 28894701, 2017). "As expected, triglyceride (TG), non-esterified fatty acid (NEFA), fasting glucose, and circulating insulin levels highly increased in the db/db mice compared with the db/m mice, confirming the development of dyslipidemia and insulin resistance in the db/db mice." (PMID 28129657, 2017). "Given the epidemiological evidence showing a significant inverse relation between dairy product intake and metabolic syndrome, improvements in peripheral insulin sensitivity with EPI can be expected, as EPI contained > 2-fold higher dairy products, compared to RPI." (PMID 28713581, 2017). "Poor insulin sensitivity is associated with T2DM and metabolic syndrome." (PMID 28673352, 2017). "Another interesting observation was that plasma insulin peaked before plasma TG peaked, which suggests that these two hallmarks of metabolic syndrome are not similarly linked to body weight gain over time." (PMID 29038350, 2017). "Previous studies showed that animals fed during the light phase exhibit an increased body weight and food consumption, alterations in leptin, insulin, corticosterone, glucose, and free fatty acid levels in plasma, fat accumulation, liver steatosis, and metabolic syndrome." (PMID 29375476, 2017). "It is well documented that testosterone replacement therapy improves these conditions in patients with manifest testosterone deficiency and numerous studies have demonstrated increased insulin sensitivity, decreased systemic inflammation and recovery of components of the metabolic syndrome." (PMID 28673265, 2017). "However, these TWEAK knock-out mice were protected from dyslipidemia and ectopic fat deposition, exhibiting enhanced whole body insulin action and glucose tolerance, as well as improved insulin signaling in liver and muscle." (PMID 28809783, 2017). "Rodent models of fructose intake are widely used to mimic (totally or in part) metabolic syndrome characteristics (e.g., increased visceral adiposity, increased circulating triacylglycerol, increased glycemia, reduced insulin sensitivity, and elevated blood pressure)." (PMID 28929113, 2017). "Thus, hyperinsulinemia and fasting insulin hypersecretion abated, dyslipidemia reversed, and the circulating concentrations of MCP-1 and IL-6 (but not TNFα) decreased." (PMID 28827671, 2017). "The excessive accumulation of triacylglyceride (TAG)-rich lipid droplets (LDs) in adipose tissue, liver, and muscle is linked to multiorgan impaired insulin sensitivity, diabetes, atherogenic dyslipidemia, and nonalcoholic fatty liver disease." (PMID 27884961, 2017). "The aqueous extract of Ilex latifolia Thunb treatment reversed body weight gain, serum levels of TC, LDL-c, HDL-c, ALT, AST, and ALP, and glucose tolerance and insulin sensitivity in mice, suggesting that Ilex latifolia Thunb prevents the development of metabolic syndrome." (PMID 29116160, 2017). "A gene that may be involved in the development of metabolic syndrome is the gene codifying for insulin itself (INS)." (PMID 28615046, 2017). "NC members had significantly lower fasting insulin (P < 0.001) and lower HbA1c (P = 0.008), higher levels of 25 hydroxy-vitamin D (P = 0.001), and vitamin E:cholesterol ratio (P < 0.001), and lower prevalence of metabolic syndrome (P = 0.02) compared to CC." (PMID 28399838, 2017). "Second, the traits of metabolic syndrome are factors highly prevalent in hypertensives as well as in kidney stone formers, so insulin resistance may be a common pathophysiological mechanism." (PMID 29187160, 2017).